ADAMTS13 (ADAM metallopeptidase with thrombospondin type 1 motif 13)
Diseases named in the same sentence as ADAMTS13 in open-access papers (continued):
Sharing a sentence is not in itself a finding about the gene and the disease.
Thrombocytopenia (continued). "In addition, given the presumed role of excessive VWF-platelet interaction in thrombocytopenia in severe leptospirosis, novel therapies aimed at preventing this interaction, including recombinant ADAMTS13, might also have some therapeutic value." (PMID 28934202, 2017). "Some patients may require monthly plasma infusions to restore ADAMTS13 and prevent symptomatic episodes, while others only require prophylactic therapy under risky conditions such as surgery, infections, pregnancies and presentation of thrombocytopenia." (PMID 28443948, 2017). "Additionally, excess VWF and ADAMTS13 deficiency are features of acute melioidosis, but are not the primary drivers of thrombocytopenia in melioidosis." (PMID 28296884, 2017). "Nevertheless, our study has clearly shown that the ratio of VWF : RCo/ADAMTS13 : AC progressively increases with the worsening of chronic liver diseases, further intensifying an enhanced thrombogenesis with the progression of liver dysfunction and thrombocytopenia." (PMID 21994870, 2011). "While the classical pentad of symptoms, MAHA, and thrombocytopenia can lead to an increased suspicion for TTP, ADAMTS13 enzyme levels must also be obtained to support this diagnosis." (PMID 41209993, 2025). "Finally, case No. 5, who had a prolonged PFA-100 closure time without thrombocytopenia and was initially thought to have a platelet function disorder, was found to carry a heterozygous pathogenic variant in the ADAMTS13 gene and showed a mild bleeding phenotype." (PMID 40941697, 2025). "She exhibited severe anemia, thrombocytopenia, and symptoms suggestive of immune-mediated TTP with markedly reduced ADAMTS13 activity." (PMID 41466911, 2025). "Thrombocytopenia was more severe and microvascular VWF-rich microthrombi in the ADAMTS13 −/− zebrafish group more present compared to the wild type group." (PMID 36769407, 2023). "In patients with relapsed or refractory TTP despite treatment with ADAMTS13 inhibitors, patient reevaluation is important to identify other potential etiologies of MAHA and thrombocytopenia." (PMID 35615090, 2022). "Decreased ADAMTS13 and increased VWF levels are relevant in TTP, which clinically manifests itself as thrombocytopenia, micro-angiopathic hemolytic anemia, fever, neurological symptoms and renal insufficiency due to the formation of microthrombi." (PMID 34134634, 2021). "It is known that in patients with liver cirrhosis, thrombocytopenia is rebalanced by increased levels of factor VIII and von-Willebrand factor and decreased levels of ADAMTS13." (PMID 32807080, 2020). "Overall, thrombocytopenia in ALF is compensated by elevated levels of vWF, reduced ADAMTS-13 levels and presence of platelet-derived extracellular vesicles that partially offset the impact of low platelet count." (PMID 33425821, 2020). "In severe sepsis, decreased ADAMTS13 activity is correlated with greater adhesion capacity of ULVWF and higher degree of thrombocytopenia as well as severity of critical illnesses and organ dysfunction." (PMID 30127669, 2018). "Because ADAMTS13 assay is often sent to a reference laboratory, most patients with unexplained MAHA and thrombocytopenia are started on plasma exchange (PLEX)." (PMID 29399327, 2018). "Laboratory investigations revealed MAHA, thrombocytopenia, elevated serum, and LDH, and an ADAMTS13 assay confirmed secondary TTP." (PMID 30223886, 2018). "It is hypothesized that sepsis-associated thrombocytopenia is a result of platelet consumption due to aggregation of platelets in the microcirculation and thrombotic microangiopathy due to incomplete cleavage of ULVWF multimers as a consequence of ADAMTS-13 deficiency." (PMID 23537039, 2013). "Early detection requires the timely diagnosis of unexplained thrombocytopenia, hemolysis, and neurologic symptoms in the absence of hypertension or abnormal coagulation, which should prompt immediate ADAMTS13 testing." (PMID 42306559, 2026).
Thrombocytopenia (continued). "One patient had persistently low ADAMTS13 activity (<20%); this was accompanied by mild thrombocytopenia (platelets < 150 × 109/L) in two instances but no signs of end-organ injury that would be consistent with a relapse of iTTP." (PMID 39941363, 2025). "Evaluation revealed thrombocytopenia, hemolytic anemia, and acute kidney injury with low C3, normal C4 & ADAMTS13 activity and positive anti-complement factor H antibody." (PMID 40443860, 2025). "In retrospect, we should consider the diagnosis of aHUS in the presence of thrombocytopenia and acute kidney injury, especially when the ADAMTS13 came back negative." (PMID 38745129, 2024). "Patients in remission who retain low ADAMTS13 levels, yet do not experience thrombocytopenia, suggest this mechanism." (PMID 38540234, 2024). "cTTP is suspected if the patient presents with thrombocytopenia and ADAMTS13 activity < 10% in the absence of ADAMTS13 inhibitors." (PMID 37689812, 2023). "TTP was lower on the differential as the patient had elevated platelets, not thrombocytopenia, and her ADAMTS13 level resulted at 75%." (PMID 40041277, 2023). "While hemolytic anemia does not seem to be present and thrombocytopenia is usually mild in patients with severe COVID-19, imbalance in the ADAMTS13-VWF axis has been repeatedly documented." (PMID 37333991, 2023). "This partial hemostasis due to lone activation of the ULVWF path is characterized by consumptive thrombocytopenia, overexpressed ULVWF/VWF/VWF antigen and increased activity of FVIII due to their endothelial release, resulting in relative ADAMTS13 insufficiency." (PMID 36143988, 2022). "He never achieved detectable ADAMTS13 activity level while receiving caplacizumab therapy; however, interestingly he exhibited significant improvement in hemolytic anemia, thrombocytopenia, and overall functional status." (PMID 35479064, 2022). "We included three patients presenting MAHA and thrombocytopenia in the absence of kidney failure, with an ADAMTS13 activity of between 10% and 30% and positive title of IgG anti‐ADAMTS13 antibodies." (PMID 35845285, 2021). "The lack of thrombocytopenia in the majority of the patients with low ADAMTS13 activity argues against TMA." (PMID 33709050, 2021). "In particular, the markedly elevated D-dimer levels, along with mildly reduced ADAMTS13 activity and lack of thrombocytopenia argues against TTP or TMA." (PMID 33709050, 2021). "Hematologists have been puzzled when encountered acquired TTP-like syndrome with negative ADAMTS13 antibody and phenotype of thrombocytopenia and MAHA." (PMID 30127669, 2018). "Moreover, all four patients who had unexplained events of thrombocytopenia before the diagnosis of TTP, corresponding to subclinical episodes of the disease, had IgG4-dominant anti-ADAMTS13 antibody response at the time of the first clinical acute episode." (PMID 30061898, 2018). "Previous report demonstrates that excessive sFlt1 together with lack of Adamts13 develops hemolysis and thrombocytopenia in mice." (PMID 29311569, 2018). "Low baseline ADAMTS13 activity of 10%, regardless to detection of anti-ADAMTS13 autoantibodies, strongly supports the diagnosis of TTP in a patient with thrombocytopenia and microangiopathitic anemia providing that a detailed evaluation has ruled out other causes of thrombotic microangiopathy." (PMID 28791286, 2017). "We speculate that biomass-related IL-6 may contribute to impaired ADAMTS13 activity and accumulation of UL-VWF multimers, and may thereby contribute to microvascular dysfunction, thrombocytopenia and disease severity in vivax malaria." (PMID 25569250, 2015). "Recent data provide evidence that an altered ADAMTS13 activity and a subsequent shift in the multimeric pattern of VWF may contribute to thrombocytopenia and microcirculatory failure due to TMA, which results in organ dysfunction including AKI." (PMID 25960882, 2014).
Thrombocytopenia (continued). "The physician should note that although cTTP always involves severely decreased ADAMTS13 activity, thrombocytopenia and other typical signs and symptoms of TTP may not always be detectable in patients without acute attacks." (PMID 37689812, 2023). "If ADAMTS13 activity drops to 10–20% in the absence of thrombocytopenia and other signs of microangiopathy, low dose corticosteroids may be considered in an attempt to increase ADAMTS13 activity." (PMID 36926315, 2023). "In addition to inflammation, endotheliopathy is characterized by the increased activity of FVIII, overexpressed ULVWF/VWF antigen, and insufficient ADAMTS13 activity, which activates the ULVWF path of hemostasis, leading to consumptive thrombocytopenia and microthrombosis." (PMID 36143988, 2022). "Although thrombocytopenia was not common in our cohort, evidence of platelet consumption in peripheral blood smears (large immature platelets and platelet clumps) and decreasing platelet trajectories was prevalent among patients with low ADAMTS13 activity." (PMID 33709050, 2021). "Conversely, ADAMTS13 activity was normal, and there was no thrombocytopenia." (PMID 33363289, 2021). "Despite the low prevalence of TTP, the finding in a pregnant woman of the triad consisting of anemia, thrombocytopenia, and neurological changes should prompt measurement of the metalloprotease ADAMTS-13 in order to rule out or confirm diagnosis of TTP and evaluate the best therapeutic option." (PMID 23628258, 2013). "However in early experimental malaria, raised vWF and thrombocytopenia were not accompanied by a change in ADAMTS13 activity." (PMID 19450727, 2009). "Due to the triad of microangiopathic hemolysis, thrombocytopenia, and organ damage, we proposed the diagnostic hypothesis of TMA (ADAMTS-13 dosage was not available in our hospital at that time), and we started fresh frozen plasma replacing (10 mL/Kg, twice a day) with subsequent plasmapheresis." (PMID 38808867, 2024). "We excluded thrombotic microangiopathy as a potential cause of the thrombocytopenia (normal LDH, no fragmented red blood cells, continuously controlled hypertension, no proteinuria) and measured a normal ADAMTS13 level and activity, no antibodies against ADAMTS13, and a stable creatinine." (PMID 33914175, 2021). "Importantly, we were unable to detect microthrombi in the lung sections of Adamts13−/−, nor did we observe thrombocytopenia or hemolysis indicative of TTP, which is in line with previous observations that ADAMTS-13 deficiency is not sufficient to induce TTP in mice." (PMID 28775254, 2017). "In the absence of ADAMTS13, platelet-rich thrombi form in the microcirculation, producing microangiopathic hemolytic anemia (MAHA), thrombocytopenia, and ischemic organ injury." (PMID 41458739, 2025). "Even though the patient presented with anemia, thrombocytopenia, renal dysfunction, and neurological deficits, the diagnosis of TTP was made on the basis of ADAMTS13 <5% since the blood smear lacked pathognomonic schistocytes and evidence of hemolysis." (PMID 37038584, 2023). "On admission, laboratory tests revealed a SCr of 187 μmol/L; eGFR 42 mL/min/1.73 m2, mild thrombocytopenia in the absence of schistocytes, negative direct antiglobulin test (DAT), and normal ADAMTS13 activity." (PMID 35615072, 2022). "To date, the assessment of ADAMTS-13 activity in pregnant women with thrombocytopenia has not been performed systematically, and the prevalence of TTP in pregnant women with thrombocytopenia remains uncertain." (PMID 26081109, 2015). "However, if VWF were the main driver of thrombocytopenia in melioidosis, then it is surprising that VWF antigen, VWF propeptide and ADAMTS13 levels do not correlate with mortality." (PMID 28296884, 2017).
thrombotic microangiopathy (136 papers, 2009 to 2026). The syndromes of microangiopathic hemolytic anemia, thrombocytopenia, and variable signs of organ impairment, due to platelet aggregation in the microcirculation. "Immune-mediated thrombotic thrombocytopenic purpura (iTTP) is a life-threatening thrombotic microangiopathy caused by an autoimmune-driven deficiency of ADAMTS-13." (PMID 41567164, 2026). "Severe genetic deficiency of ADAMTS13 causes congenital thrombotic thrombocytopenic purpura, a life-threatening thrombotic microangiopathy." (PMID 41051174, 2025). "Severe ADAMTS13 deficiency causes congenital thrombotic thrombocytopenic purpura (cTTP, or Upshaw-Schulman syndrome), a rare but life-threatening thrombotic microangiopathy." (PMID 41051174, 2025). "Immune-mediated thrombotic thrombocytopenic purpura (iTTP) is a life-threatening thrombotic microangiopathy resulting from severe ADAMTS13 deficiency." (PMID 41333464, 2025). "TTP is a rare but life-threatening thrombotic microangiopathy caused by a severe deficiency in ADAMTS13, a metalloprotease responsible for cleaving ultra-large von Willebrand factor (vWF) multimers." (PMID 40827194, 2025). "In thrombotic microangiopathies, the primary cause of ADAMTS13 deficiency is autoantibodies that disrupt its function." (PMID 40725629, 2025). "The detection of ADAMTS13 deficiency remains essential for identifying thrombotic microangiopathies that produce life-threatening blood clots through impaired VWF cleavage." (PMID 40725629, 2025). "Congenital thrombotic thrombocytopenic purpura (cTTP; Upshaw-Schulman syndrome) is an ultra-rare hereditary thrombotic microangiopathy caused by biallelic pathogenic variants in ADAMTS13." (PMID 41458739, 2025). "Congenital thrombotic thrombocytopenic purpura (cTTP; Upshaw-Schulman syndrome) is a rare hereditary thrombotic microangiopathy characterized by severe deficiency of ADAMTS13 activity." (PMID 41458739, 2025). "An in vitro model of thrombotic microangiopathy was developed in which Shiga toxin 2- and E. coli O157 lipopolysaccharide-stimulated human blood cells combined with ADAMTS13-deficient plasma were perfused over glomerular endothelial cells." (PMID 38178089, 2024). "Severe ADAMTS13 deficiency and the presence of inhibitory antibodies to ADAMTS13 is essential for the diagnosis of iTTP, and to differentiate it from other thrombotic microangiopathies (TMAs)." (PMID 39274365, 2024). "Background/Objectives: Immune thrombotic thrombocytopenic purpura (iTTP) is a thrombotic microangiopathy caused by the formation of anti-ADAMTS13 antibodies." (PMID 39518700, 2024). "Dysregulation of the balance between vWF and ADAMTS13 has been implicated in endothelial dysfunction and thrombotic microangiopathy, which are central features of preeclampsia." (PMID 38673014, 2024). "A significant proportion of patients with thrombotic microangiopathies and severe ADAMTS13 deficiency have anti-ADAMTS13 IgG, highlighting the usefulness of IgG detection in these clinical settings." (PMID 39001098, 2024). "A correct differential diagnosis to distinguish TTP from other thrombotic microangiopathies is crucial because mostly only patients with severe ADAMTS13 deficiency are likely to respond to plasma exchange (PE)." (PMID 39768494, 2024). "In the case of a suspected acute episode of thrombotic microangiopathy, the pretest likelihood of a severe ADAMTS13 deficiency can be estimated using the French and PLASMIC scores, both validated for adults." (PMID 39233868, 2024). "TTP is a rare thrombotic microangiopathy, caused by the deficiency of a specific protease targeting the von Willebrand factor, called ADAMTS13." (PMID 37830631, 2023). "cTTP is an autosomal recessive thrombotic microangiopathy caused by a biallelic mutation in the ADAMTS13 gene, located on chromosome 9q34, resulting in severe ADAMTS13 deficiency (activity<10%)." (PMID 37822445, 2023).
thrombotic microangiopathy (continued). "The hemolytic uremic syndrome is thrombotic microangiopathy associated with severe renal impairment and normal or slightly reduced ADAMTS13 activity." (PMID 35949449, 2022). "TTP is a rare cause of thrombotic microangiopathy defined by clinical criteria, biological markers of intravascular hemolysis, and severe ADAMTS13 deficiency." (PMID 35479064, 2022). "Several clinical scoring systems have been developed for the differential diagnosis of thrombotic microangiopathies (TMAs), all to predict and identify patients with ADAMTS13 deficiency and to start treatment as soon as possible." (PMID 33161686, 2021). "Upshaw–Schulman syndrome (USS) is an autosomal recessive disease characterized by thrombotic microangiopathies caused by pathogenic variants in ADAMTS13." (PMID 34789164, 2021). "Immune-mediated thrombotic thrombocytopenic purpura (iTTP) is a rare, life-threatening thrombotic microangiopathy caused by severe ADAMTS13 (a disintegrin and metalloproteinase with thrombospondin motifs 13) deficiency, recurring in 30–50% of patients." (PMID 33096882, 2020). "Severe ADAMTS13 deficiency leads to formation of the pathological lesion termed thrombotic microangiopathy (TMA) which affects renal function due to occluded glomerular capillaries containing VWF-rich microthrombi." (PMID 28139439, 2017). "Further studies however are required to confirm the mechanisms underlying ADAMTS13 deficiency in vivax malaria, and to investigate the role of thrombotic microangiopathy." (PMID 25569250, 2015). "Deficient proteolysis of ULvWF due to reduced ADAMTS-13 activity results in disseminated platelet-rich thrombi in the microcirculation seen in thrombotic microangiopathies (TMA)." (PMID 23537039, 2013). "Secondary forms of thrombotic microangiopathies, which occur in the context of pregnancy, autoimmune disease, malignancy, bone marrow transplantation or use of certain medications, are associated with mildly reduced or even normal ADAMTS13 activity." (PMID 41160661, 2025). "Therefore, our research endeavors to delve into the roles of ADAMTS13 and the complement system, both of which have been implicated in endothelial dysfunction and thrombotic microangiopathy, key features of PE and HELLP syndrome." (PMID 38673014, 2024). "Sepsis, particularly septic shock, is another clinical condition in which thrombotic microangiopathy may occur, and this is often associated with relatively decreased levels of ADAMTS13 but that are usually greater than 10% of normal." (PMID 39200994, 2024). "Reduced ADAMTS13 activity concomitant with increased plasma VWF levels has been observed in thrombotic microangiopathies (TMAs) associated with systemic inflammation, such as in severe sepsis, sepsis-induced disseminated intravascular coagulation (DIC), malignancy, and autoimmune diseases." (PMID 33343584, 2020). "The role of plasma exchange has been well established in other conditions such as thrombotic thrombocytopenia purpura, a thrombotic microangiopathy associated with severely depleted levels of A Disintegrin-like and Metalloproteinase with Thrombospondin type-1 Motifs 13 (ADAMTS-13)." (PMID 25527094, 2014). "Both TTP and sepsis are associated with thrombotic microangiopathy and severe ADAMTS-13 deficiency." (PMID 23537039, 2013). "While looking into the role of ADAMTS13 in common diseases associated with thrombotic microangiopathies, it was found that severe secondary ADAMTS13 deficiency is also present in patients with sepsis, connective tissue diseases, liver cirrhosis and acute inflammation." (PMID 23537039, 2013). "Severe ADAMTS13 deficiency occurs in 13% to 75% of thrombotic microangiopathies (TMA)." (PMID 20436664, 2010). "Based on these observations, the vWF/ADAMTS13 imbalance has been proposed to be causally related both to the prothrombotic tendency and to the microvascular pulmonary thrombosis, which subtend to a form of thrombotic microangiopathy (TMA) observed in severe COVID-19 patients." (PMID 34834519, 2021).